ASGR1 (asialoglycoprotein receptor 1)
Description:
Transmembrane protein predominantly expressed on hepatocytes that plays a key role in endocytosis of plasma glycoproteins that lack terminal sialic acid residues. Specifically recognizes terminal galactose and N-acetylgalactosamine residues, facilitating the clearance of desialylated glycoproteins from circulation. Plays thereby a role in a variety of physiological processes, such as removal of desialylated platelets, elimination of activated lymphocytes and maintenance of serum glycoprotein homeostasis. Plays a role in the removal of desialylated platelets by activating a feedback loop regulating thrombopoietin (TPO) expression via the JAK2-STAT3 signaling pathway. Contributes also to recognition and elimination of activated lymphocytes by hepatocytes that can act as cytotoxic effectors. May also play a physiological role in the regulatory network of lipid homeostasis (By similarity). Upon ligand binding, the receptor-ligand complex is internalized and trafficked to a sorting organelle, where dissociation occurs. The receptor is then recycled back to the cell surface. (Microbial infection) Plays an essential role in ACE2-independent SARS-CoV-2 entry by acting as alternate receptor.
Synonyms: HL-1; CLEC4H1; ASGPR; ASGPR1
Tractability: Small molecule: a structure with a bound ligand is known. Antibody: UniProt places it where antibodies can reach, with high confidence; its Gene Ontology location is reachable by antibodies, with high confidence; UniProt predicts a signal peptide or a membrane-spanning region. PROTAC: its protein half-life has been measured. Other modalities: a drug acting on it is in phase 2 or 3 trials.
Target class: Membrane receptor
Gene: Protein-coding gene on chromosome 17 (7,172,535 to 7,179,648, reverse strand). Ensembl gene ENSG00000141505.
Subcellular location: Cell membrane (Isoform H1a); Secreted (Isoform H1b)
Subcellular location (Human Protein Atlas): Vesicles; Cell Junctions; Predicted to be secreted
Pathways (Reactome):
Metabolism of proteins: Asparagine N-linked glycosylation
Gene Ontology:
Molecular function: pattern recognition receptor activity; protein binding; asialoglycoprotein receptor activity; D-mannose binding; fucose binding; identical protein binding
Biological process: receptor-mediated endocytosis; immune response
Cellular component: plasma membrane; external side of plasma membrane; extracellular region
Genetic constraint (gnomAD): Loss-of-function variants: 35 observed, 35.08 expected, observed/expected ratio (o/e) 1, 90% interval 0.76 to 1.32. The upper end of that interval is the gene's LOEUF score, 1.32, which puts it in group 5 of 6, group 1 being the genes least tolerant of losing a copy. Missense variants: 396 observed, 398.35 expected, observed/expected ratio (o/e) 0.99, 90% interval 0.92 to 1.08. Synonymous variants: 142 observed, 164.83 expected, observed/expected ratio (o/e) 0.86, 90% interval 0.75 to 0.99.
Homologues: Orthologues: chimpanzee ASGR1 (99% identical), macaque ASGR1 (98% identical), pig ASGR1 (82% identical), dog ASGR1 (82% identical), guinea pig ASGR1 (81% identical), rat Asgr1 (78% identical), mouse Asgr1 (77% identical), rabbit ASGR1 (52% identical), tropical clawed frog clec10a (36% identical), Drosophila melanogaster tfc (20% identical), Caenorhabditis elegans clec-266 (18% identical), Caenorhabditis elegans clec-87 (14% identical), and 7 more. Paralogues in human: ASGR2 (59% identical), CLEC10A (57% identical), CLEC17A (24% identical), CLEC4A (22% identical), FCER2 (22% identical), CD209 (22% identical), CLEC6A (21% identical), CD207 (20% identical), CLEC4E (20% identical), CLEC4M (20% identical), CLEC4F (20% identical), CLEC4G (20% identical), and 2 more.
Diseases named in the same sentence as ASGR1 in open-access papers:
ASGR1 is named in the same sentence as 82 diseases in open-access papers, as found by Europe PMC text mining. Sharing a sentence is not in itself a finding about the gene and the disease. The quoted sentences say what the papers report.
hepatocellular carcinoma (65 papers, 1999 to 2025). A malignant tumor that arises from hepatocytes. "We proved that OF binds to ASGR1/2 receptors on hepatoma cell, we also provided strong evidence that OF activates phosphorylation of STAT3, and then pSTAT3 will bind to P1 promoter of HNF4A, transcriptionally regulates the level of HNF4A, P1 isoform." (PMID 33377648, 2020). "For instance, ASGR1 inhibitors could suppress metastasis in hepatocellular carcinoma, whereas activators might restore metabolic homeostasis or enhance liver regeneration in specific disease contexts." (PMID 40429734, 2025). "Studies have reported that low LASS2 expression is associated with a poor prognosis for patients with hepatocellular carcinoma (HCC) and suggested that the combination of LASS2 and TGF-β1 or ASGR1 may assist in predicting the prognosis." (PMID 37963859, 2023). "Previous studies have shown that a high level of ASGR1 inhibits migration and invasion of hepatocellular carcinoma (HCC) cells, which may be related to immune activities in liver diseases and infections." (PMID 38034398, 2023). "In this study we have demonstrated the suitability of two liver-specific biomarkers (ASGR1 and miR-122-5p) for the characterization of circulating epithelial cells (CECs) from liver cirrhosis (LC) and hepatocellular carcinoma (HCC) patients as prognostic biomarkers." (PMID 36518850, 2022). "Knockdown of ASGR1 or HNF4A reverse the OF mediated hepatoma cell proliferation inhibition effect." (PMID 33377648, 2020). "We also demonstrated that OF binds to ASGR1, activating pSTAT3 which specifically binds to P1‐HNF4A promoter in HepG2 hepatoma cells." (PMID 33377648, 2020).
liver cancer (28 papers, 2012 to 2025). An epithelial or non-epithelial malignant neoplasm that arises from the liver. "This approach utilizes the galactose recognition capability of ASGR1 to achieve liver cancer cell targeting and exerts potent anti-cancer effects by inducing ferroptosis while significantly reducing toxicity." (PMID 40852369, 2025). "Among the identified inhibitors, Ansamitocin P-3 exhibits particularly pronounced inhibitory effects on ASGR1 protein in both liver cancer cell lines, with its efficacy increasing over extended treatment durations." (PMID 40429734, 2025). "For instance, small-molecule drugs conjugated with Gal or GalNAc, such as betulin, can specifically recognize and enter ASGR1-expressing liver cancer cells, exerting targeted anti-tumor effects through mechanisms like oxidative stress." (PMID 40852369, 2025). "Additionally, glycopolymer-based nanocarriers mediated by ASGR1 have been designed to precisely deliver suicide gene therapies in combination with chemotherapeutic drugs, effectively inhibiting liver cancer cell growth and showing promising clinical potential." (PMID 40852369, 2025). "Additionally, ASGR1 interacts with longevity assurance homolog 2 (LASS2) to suppress vacuolar-type H+-ATPase (V-ATPase) activity, reducing HCC cell migration and invasion, further supporting the role of ASGR1 as a metastasis suppressor in liver cancer." (PMID 40852369, 2025). "The most progress regarding a practicable use of large EVs has been achieved with the determination of large EVs positive for Annexin V, epithelial cell adhesion molecule (EpCAM), CD133 and asialoglycoprotein receptor 1 (ASGPR1) as a highly specific parameter for liver cancers diagnosis." (PMID 33080904, 2020). "Meanwhile, ASGR1+ tumor-associated microparticles (taMPs) are significantly elevated in the peripheral blood of patients with HCC and cholangiocarcinoma, suggesting their potential as a novel non-invasive diagnostic tool for distinguishing liver cancer from liver cirrhosis." (PMID 40852369, 2025). "In the context of liver cancer, the role of ASGR1 as tumor suppressor was first suggested via its interaction with LASS2 (longevity assurance homolog 2 of yeast LAG1) and more recently by its association with DNA methylation, confirming the prior findings of loss of ASGR1 expression in HCC tissue." (PMID 36518850, 2022). "AnnexinV+ EpCAM+ Human Asialoglycoprotein Receptor 1 (ASGPR1+) MVs were able to distinguish patients with cirrhosis and liver cancer (HCC or cholangiocarcinoma) from those with no malignancy, and this was confirmed by the drop in the concentration 7 days after curative resection." (PMID 36230554, 2022).
liver diseases (20 papers, 2010 to 2025). "ASGR1 binds to the circulating liver disease biomarker Golgi Protein 73 (GP73) and mediates its endocytosis for subsequent lysosomal degradation." (PMID 40852369, 2025). "Considering the variability of ASGR1 expression among liver disease patients, it is recommended to use companion diagnostics to stratify patients during clinical application of ASGR1-targeted therapies, thereby improving therapeutic outcomes." (PMID 40852369, 2025). "Therefore, targeting ASGR1 or its associated signaling axis holds promise as a novel strategy for controlling hepatic inflammatory responses and blocking macrophage polarization, and warrants further investigation in broader models of inflammatory liver disease." (PMID 40852369, 2025). "ASGR1 agonists or multivalent GalNAc ligands may be used to enhance TPO expression, thereby improving liver disease–associated thrombocytopenia." (PMID 40852369, 2025). "By way of example, liver-derived EVs can be selectively captured via the hepatocyte-specific surface protein asialoglycoprotein receptor 1 (ASGR1), and may be of great value to the study of drug metabolism or liver diseases." (PMID 33668220, 2021). "ASGR1-deficient pigs could be a valuable animal model to explore the underlying mechanisms of CVD as well as to test the genetic susceptibility and therapeutics for liver diseases." (PMID 34762653, 2021). "Mechanistically, ASGR1 physically interacts with the ER stress mediator GP73, a circulating glycoprotein and established serum marker for liver diseases such as HBV, HCC and liver cirrhosis, thereby facilitating its degradation." (PMID 38459023, 2024). "Similarly, research has demonstrated the efficacy of using asialoglycoprotein receptor 1 (ASGR1) to purify hepatocyte-derived exosomes, significantly improving liver disease biomarker detection." (PMID 39061191, 2024).
Cirrhosis (18 papers, 2017 to 2025). A chronic disorder of the liver in which liver tissue becomes scarred and is partially replaced by regenerative nodules and fibrotic tissue resulting in loss of liver function. "To investigate the potential association between ASGR1 and liver injury, we first determined hepatic ASGR1 expression in patients diagnosed with liver fibrosis or cirrhosis." (PMID 38459023, 2024). "In this study, we found reduced hepatic ASGR1 expression in patients with liver fibrosis or cirrhosis and in mice exhibiting liver injury." (PMID 38459023, 2024). "Here we show that asialoglycoprotein receptor 1 (ASGR1), a lectin specifically expressed in the liver, is downregulated in patients with liver fibrosis or cirrhosis and male mice with liver injury." (PMID 38459023, 2024). "Later work demonstrated that the combination of surface markers, Annexin V, EpCAM, ASGR1 and CD133, could be used to identify tumour-associated EVs in circulation and distinguish between liver cancers (HCC and cholangiocarcinoma) and tumour-free cirrhosis." (PMID 35397694, 2022). "In human, the expression of ASGR1 was observed to be significantly decreased in patients with NAFLD and NASH as well as in hepatic cirrhosis or in highly proliferative liver tumors." (PMID 38281933, 2024). "EP from resident cells, such as ASGR1+ EP, first emerged as a biomarker for distinguishing patients with liver malignancies from patients with cirrhosis but no malignancy." (PMID 34025656, 2021).
coronary artery disease (11 papers, 2016 to 2026). "In the present study, plasma proteomics analysis revealed ASGR1 to be a risk factor for ischemic heart disease." (PMID 38539180, 2024). "Recent studies have shown that loss-of-function mutations in hepatic asialoglycoprotein receptor 1 (ASGR1) are associated with low levels of circulating cholesterol and a reduced risk of coronary artery disease (CAD)." (PMID 37667265, 2023). "Asialoglycoprotein receptor 1 (ASGR1) is associated with lipid metabolism and coronary artery disease (CAD) risk, but its expression patterns, diagnostic performance, and prognostic significance in hypertensive patients with CAD remain unelucidated." (PMID 42048115, 2026). "Asialoglycoprotein receptor 1 (ASGR1) is emerging as a potential drug target to reduce low-density lipoprotein (LDL)-cholesterol and coronary artery disease (CAD) risk." (PMID 37400795, 2023). "A human population genetic study provided evidence that variant asialoglycoprotein receptor 1 (ASGR1) is associated with lower non–HDL-c content and reduced risk of coronary artery disease (CAD), indicating a potential target for CVD prevention and treatment." (PMID 34622799, 2021). "In humans, ASGR1 del12 variant has a larger effect on the risk of coronary artery disease than is predicted by its effect on levels of non-HDL cholesterol." (PMID 34762653, 2021). "Human heterozygote carriers of ASGR1 deletions exhibit ∼34% lower risk of coronary artery disease and ∼10% to 14% reduction of non-HDL cholesterol." (PMID 34508778, 2021). "Variants in ASGR1 are associated with lower non-high-density lipoprotein (non-HDL) cholesterol levels and a reduced risk of coronary artery disease." (PMID 38812487, 2024). "An important genetic study on the Icelandic population has recently identified a strong link between a new gene – ASGR1 (for asialoglycoprotein receptor) – mutation, plasma non-HDL-C levels, and coronary heart disease (CHD)." (PMID 29043262, 2016). "ASGR1 loss-of-function mutations are linked to a 0.4 mmol/l decrease in circulating non-high-density lipoprotein cholesterol (non-HDL-C) and a 34% reduction in the incidence of coronary artery disease (CAD)." (PMID 38539180, 2024). "Variants in ASGR1 are associated with lower non-high-density lipoprotein (non-HDL)-cholesterol and a lower risk of coronary artery disease (CAD)." (PMID 37400795, 2023).
atherosclerosis (10 papers, 2021 to 2025). A disease characterized by the build-up of fatty material and calcium deposition in the arterial wall resulting in partial or complete occlusion of the arterial lumen. "In this study, we investigated the impact of ASGR1 deficiency (ASGR1−/−) on atherosclerosis by evaluating its effects on plaque formation, lipid metabolism, circulating immunoinflammatory response, and circulating N-glycome under the hypercholesterolemic condition in ApoE-deficient mice." (PMID 39616371, 2024). "At present, the roles and mechanisms of ASGR1 in the development of viral infectious diseases, tumors, atherosclerosis, and other diseases have been well recognized." (PMID 40852369, 2025). "Gene set enrichment analyses (GSEAs) showed the lipid and atherosclerosis pathway was significantly enriched in ASGR1+/−pig livers (NES = 1.471, p = 0.006)." (PMID 39055948, 2024). "Further experiments are needed to demonstrate the beneficial impact of ASGR1 inhibition-induced autophagy on its protective effect against atherosclerosis." (PMID 39055948, 2024). "As in humans with ASGR1 variants, ASGR1 deficiency in pigs substantially reduces circulating non-HDL-C levels and thus protects against HFHC diet-induced atherosclerosis." (PMID 34762653, 2021). "Together, these results show that ASGR1 deficiency protects against HFHC-induced hypercholesterolemia and atherosclerosis in pigs." (PMID 34762653, 2021). "One recent study reported that ASGR1 affected the plaque formation and atherosclerosis by intimal macrophages." (PMID 34762653, 2021). "The role of ASGR1 in lipid regulation may have profound implications for atherosclerosis (AS) and cardiovascular disease (CVD)." (PMID 40852369, 2025). "However, further studies are needed to reveal the role of ASGR1 in the inflammation of atherosclerosis." (PMID 38539180, 2024). "In addition, the interacting proteins identified in our study provide a better way to understand the function of ASGR1, and PON2 is a hopeful target to inhibit ASGR1 and prevent atherosclerosis." (PMID 39055948, 2024). "The interaction of ASGR1 with epidermal growth factor receptor (EGFR) activates the extracellular signal-regulated kinase (ERK) pathway, which has been linked to inflammatory regulation and atherosclerosis." (PMID 38539180, 2024). "Loss-of-function mutations in the ASGR1 gene are associated with decreased levels of non-high-density lipoprotein cholesterol and triglycerides in the blood plasma, resulting in a reduction in the risk of atherosclerosis and CVD." (PMID 38329179, 2024). "We should acknowledge, within the limitations of our study, that we have addressed atherosclerosis at a single time point (16 weeks of WTD diet) and the evaluation at a shorter time point might contribute to a better understanding the impact of ASGR1 deficiency on atherosclerosis and liver function." (PMID 39616371, 2024). "Notably, in this study, the reduction observed in non-HDL cholesterol levels was partly explaining the protection from CVD disease supporting the possibility that ASGR1 could play an additional role in lipoprotein metabolism as well as in atherosclerosis." (PMID 39616371, 2024). "Thus, targeting ASGR1 might be an effective strategy to reduce hypercholesterolemia and atherosclerosis, whereas further clinical evidence is required to assess its hepatic impact." (PMID 34762653, 2021). "To examine whether the substantial reduction of atherogenic non-HDL-C upon ASGR1 deficiency would protect pigs against atherosclerosis, we assessed atherosclerotic lesions in two-year-old ASGR1-/- pigs and their age-matched WT pigs fed a normal diet." (PMID 34762653, 2021).